KIF20A (kinesin family member 20A)
Diseases named in the same sentence as KIF20A in open-access papers (continued):
Sharing a sentence is not in itself a finding about the gene and the disease.
bladder cancer (continued). "Transwell invasion assays were performed to detect the effect of KIF20A on the invasion of bladder cancer cells, and the results showed that the number of invading cancer cells in the T24shKIF20A/5637shKIF20A group was significantly lower than that in the control group." (PMID 31093305, 2019). "KIF20A may become an independent factor that affects the prognosis of bladder cancer patients and a therapeutic target for bladder cancer." (PMID 31093305, 2019). "To demonstrate this hypothesis, we confirmed in vitro and in vivo that the high expression levels of KIF20A indeed promote the proliferation of bladder cancer cells." (PMID 31093305, 2019). "KIF20A can be an independent factor that affects the prognosis of patients with bladder cancer." (PMID 31093305, 2019). "That is, the proliferation of bladder cancer cells is inhibited after knocking down KIF20A." (PMID 31093305, 2019). "In summary, KIF20A is likely to be a potential target for cancer therapy in bladder cancer." (PMID 31093305, 2019). "More importantly, KIF20A may become an independent factor that affects the prognosis of bladder cancer patients and a therapeutic target for bladder cancer." (PMID 31093305, 2019). "We confirmed that KIF20A promotes the proliferation and metastasis of bladder cancer cells." (PMID 31093305, 2019). "KIF20A promotes the proliferation and metastasis of bladder cancer cells." (PMID 31093305, 2019). "A previous study has also documented an up-regulation of KIF20A in bladder cancer." (PMID 22724020, 2012). "In addition, overexpression of the KIF20A gene was also observed in other malignancies, such as lung and bladder cancers." (PMID 21179034, 2011). "Overall, these studies suggest that KIF20A might affect the progression of bladder cancer." (PMID 37310408, 2023). "KIF20A may be used as a molecular target for early diagnosis and precise treatment of bladder cancer and renal cell carcinoma and to provide a basis for the study of the mechanism of bladder cancer and renal carcinoma." (PMID 37310408, 2023). "The results of the colony formation assay showed that the number of cell colonies in the T24shKIF20A/5637shKIF20A group was significantly lower than that in the control group, which confirmed that the knockdown of KIF20A could effectively inhibit the proliferation of bladder cancer cells." (PMID 31093305, 2019). "Julian Kositza and colleagues conducted a study that revealed the effectiveness of combining Paprotrain, a specific inhibitor of KIF20A, with palbociclib, a well-known CDK4/6 inhibitor, in treating bladder cancer." (PMID 39272816, 2024). "We performed protein-protein interaction analysis to select five important candidate genes (BUB1B, CCNB1, CDC25A, FBXO5, KIF20A, NDC80) regulated by PLK1 in bladder cancer cells using STRING software." (PMID 29246203, 2017). "The mechanism by which KIF20A promotes the proliferation and metastasis of bladder cancer cells has not been studied in depth." (PMID 31093305, 2019).
hepatocellular carcinoma (29 papers, 2013 to 2026). A malignant tumor that arises from hepatocytes. "We found that the KIF20A gene is linked to liver cell carcinoma, necrosis, chemical- and drug-induced liver damage, weight loss, delayed effects of prenatal exposure, liver enlargement, inflammation, and proliferation." (PMID 37310408, 2023). "Moreover, KIF20A contributes to both normal and pathologic hepatocyte proliferation, and is linked to tumor aggressiveness in human hepatocellular carcinomas." (PMID 27941992, 2016). "Elevated evidence suggests that KIF20A plays an important role in hepatocellular carcinoma (HCC) progression." (PMID 39624268, 2024). "KIF20A was highly expressed in almost all of the cancer, including melanoma, hepatocellular carcinoma, esophageal squamous cell carcinoma." (PMID 36798768, 2023). "As revealed from numerous recently conducted studies, KIF20A is considered a vital gene for considerable tumors (e.g., hepatocellular carcinoma or ovarian cancer)." (PMID 36523602, 2022). "The activation of KIF20A–Gli2 axis has been reported to be crucial for hepatoma cell growth, indicating that KIF20A plays a vital role in the development of liver cancer." (PMID 33193629, 2020). "Overexpression of KIF20A is correlated with poor overall survival of hepatocellular carcinoma, lung adenocarcinoma and ccRCC." (PMID 31788359, 2019). "Silencing KIF20A could induce prostate cancer cells to death and aberrantly activated Gli2-KIF20A axis which is crucial for the growth of hepatocellular carcinoma and predicts poor prognosis in hepatocellular carcinoma." (PMID 34384030, 2021). "Studies have shown that Aberrant KIF20A expression might independently predict poor overall survival and recurrence-free survival of hepatocellular carcinoma." (PMID 32789471, 2020). "Kinesin family member 20A (KIF20A) is essential for cell proliferation and is implicated in promoting tumor progression, but its role in hepatocellular carcinoma (HCC) remains poorly studied." (PMID 39555078, 2024). "In addition KIF20A knockdown inhibited cell proliferation in hepatoma cells." (PMID 25036038, 2014). "The activation of glioma-associated oncogene family zinc finger 2 (Gli2), a central figure in Hedgehog (Hh) signaling pivotal for hepatocellular carcinoma (HCC) development, has been found to indirectly stimulate the expression of KIF20A through the activation of FOXM1." (PMID 39272816, 2024). "In hepatocellular carcinoma (HCC), inhibition of KIF20A reduced HCC growth; increased KIF20A promoted both normal and pathologic hepatocyte proliferation and was related to tumor aggressiveness." (PMID 36798768, 2023).
gastric cancer (28 papers, 2011 to 2026). A primary or metastatic malignant neoplasm involving the stomach. "Moreover, overexpression of KIF20A was tightly associated with a poor prognosis and the clinical parameters in patients with gastric cancer." (PMID 36096734, 2022). "Clinically, KIF20A is recognized for its prognostic value in melanoma, breast, bladder, cervical, ovarian, and gastric cancers, serving as a promising biomarker for tracking cancer progression." (PMID 39272816, 2024). "KIF20A had been proved to be involved in G2/M phase arrest, and played an important role in gastric cancer." (PMID 36798768, 2023). "After treatment of genistein, gastric cancer cells were arrested in G2/M phase, the expression of KIF20A was reduced." (PMID 36798768, 2023). "Several studies have recently shown a prominent increase in the level of KIF20A expression in a variety of malignancies, including breast, lung, liver, and gastric cancers." (PMID 33952272, 2021). "A number of studies have recently shown a prominent increase on the level of KIF20A expression in varieties of malignancies, including breast, lung, liver, gastric cancers, thus indicating a putative role of KIF20A in cancer development and progression." (PMID 33232285, 2020). "In recent years, some scholars have pointed out that the downregulation of KIF20A can induce gastric cancer cell mitosis (G2/M phase) arrest and enhance chemotherapy drug sensitivity." (PMID 31093305, 2019). "Recent study reported that KIF20A played an important role in anti-tumor activity of genistein, and introduced KIF20A as a potential target for drug intervention of gastric cancer." (PMID 28052097, 2017). "KIF20A was found to be overexpressed in pancreatic ductal adenocarcinoma cells and its down-regulation inhibited the growth of gastric cancer cells." (PMID 27128470, 2016). "Expression of ITGB5, TYMS, MYB, APOC1, CBX5, PLA2G2A, and KIF20A which is up-regulated in human gastric cancer tissues, was significantly decreased by vorinostat." (PMID 21931799, 2011). "Yi Sheng and collaborators have demonstrated that KIF20A’s increased expression in gastric cancer correlates with enhanced cell proliferation, poor overall survival, and higher histological grades, highlighting its oncogenic role and its potential as a prognostic and therapeutic target." (PMID 39272816, 2024). "Moreover, inhibiting KIF20A resulted in gastric cancer cell mitosis (G2/M phase) arrest and improved drug resistance to chemotherapy." (PMID 36096734, 2022). "Genistein might inhibit gastric cancer by downregulating KIF20A." (PMID 36798768, 2023). "Of these 12 genes, 7 genes highly expressed in gastric cancer tissues were down-regulated (ITGB5, TYMS, MYB, APOC1, CBX5, PLA2G2A, KIF20A) and 5 low-expressed genes were up-regulated after vorinostat treatment (SCGB2A1, TCN1, CFD, APLP1, NQO1." (PMID 21931799, 2011). "Moreover, gene expression analysis of gastric cancer identified a collection of genes (ITGB5, TYMS, MYB, APOC1, CBX5, PLA2G2A, and KIF20A) whose expression was elevated in gastric tumor tissue and downregulated more than 2-fold by vorinostat treatment in gastric cancer cell lines." (PMID 21931799, 2011). "Similarly, OS was not significantly different in patients with advanced gastric cancer treated with multiple peptides (DEPDC1, URLC10, FoxM1, Kif20A, and VEGFR1) who were A24(+) compared with A24(–)." (PMID 38993370, 2022).
colorectal cancer (23 papers, 2011 to 2026). A primary or metastatic malignant neoplasm that affects the colon or rectum. "KIF20A can inhibit ferroptosis in colorectal cancer cells, thereby reducing their sensitivity to oxaliplatin." (PMID 40136455, 2025). "The JAK/STAT3 pathway’s role in mediating the effects of KIF20A highlights its importance in colorectal cancer progression." (PMID 39272816, 2024). "KIF20A was highly expressed in the oxaliplatin-resistant cell lines and strongly correlated with survival among colorectal cancer patients." (PMID 36798768, 2023). "Meanwhile, KIF20A was associated with invasion, lymphatic node metastasis, distant metastasis, and tumor-node-metastasis (TNM) stage in colorectal cancer." (PMID 36798768, 2023). "Knockdown of KIF20A enhanced the sensitivity of colorectal cancer cells to oxaliplatin and inhibited the activation of NUAK1, a kinase related to malignant progression and poor prognosis of CRC." (PMID 36798768, 2023). "KIF20A is overexpressed in many types of cancer cells, including breast, lung, liver, pancreatic, ovarian, and colorectal cancers, as well as bladder and renal cancers." (PMID 37310408, 2023). "In colorectal cancer, increased KIF20A promoted cell proliferation, decreased KIF20A reduced cell proliferation and migration." (PMID 36798768, 2023). "Our previous studies have shown that high expression of KIF20A can significantly promote the proliferation of colorectal cancer, and it is related to the poor prognosis of colorectal cancer patients." (PMID 33754001, 2021). "KIF20A maintains a set of malignant characteristics in colorectal cancer by activating the JAK/STAT3 pathway." (PMID 34595101, 2021). "In order to explore further the function of KIF20A in vitro, we examined KIF20A expression in seven different colorectal cancer cell lines (SW480, N18, RKO, HCT-116, SW620, CACO2, and LOVO) and one normal cell line (NCM)." (PMID 31841120, 2019). "In colorectal cancer, KIF20A provokes malignant characteristics by activating the JAK/STAT pathway." (PMID 36980610, 2023). "In addition, KIF20A knockout reduces colorectal cancer cell proliferation and migration by inhibiting the JAK/STAT3 pathway." (PMID 34025420, 2021). "KIF20A could promote the growth of colorectal cancer cells via the JAK/STAT3 signalling pathway." (PMID 36096734, 2022). "Besides, inhibition of KIF20A could induce ferroptosis in colorectal cancer cells." (PMID 40914946, 2026). "Therefore, we speculate that KIF23 may play a similar role as KIF20A in colorectal cancer." (PMID 33754001, 2021). "The exploration of KIF20A has also advanced targeted therapy options, particularly in manipulating pathways such as JAK/STAT3 signaling, which are crucial for innovative treatments in colorectal cancer and other malignancies." (PMID 39272816, 2024). "Cellular ferroptosis may be induced by disrupting the KIF20A/NUAK1/PP1β/GPX4 pathway, thus overcoming the resistance of colorectal cancer to oxaliplatin." (PMID 35151318, 2022). "Additionally, KIF20A has been shown to promote proliferation of LUAD cells and mediate colorectal cancer (CRC) resistance to Oxaliplatin by inhibiting ferroptosis." (PMID 36225575, 2022). "In addition, we extracted gene expression data for KIF20A from GSE20916 in normal colorectal tissue, benign tumors, and colorectal carcinoma." (PMID 31841120, 2019).
lung carcinoma (18 papers, 2013 to 2025). "KIF20A/MKLP2 is overexpressed in many cancers, including lung cancer, raising interest in its potential as a therapeutic target." (PMID 40002279, 2025). "The functions of FOXM1 in radiosensitivity have also been investigated in lung cancer, in which it drives the expression of kinesin family member 20A (KIF20A), augmenting cell proliferation, invasion, migration, and inhibiting apoptosis." (PMID 34141616, 2021). "It has been reported that FOXM1 can enhance the radioresistance of lung cancer by inducing the expression of KIF20A." (PMID 31093305, 2019). "KIF20A was identified as one of the co‐upregulated genes among four independent lung cancer gene microarray datasets downloaded from the Gene Expression Omnibus (GEO) database." (PMID 30105795, 2018). "Phase I/II clinical trials of cancer immunotherapy KIF20A-derived short peptides in lung cancer and cholangiocellular carcinoma are now currently underway." (PMID 28081138, 2017). "Based on this result, we proposed whether KIF20A was related to the proliferation of lung cancer and affected the proliferation of lung cancer cells." (PMID 30105795, 2018). "The roles of KIF4A, KIF11 and KIF2C in lung cancer have been already reported, while the involvement of KIF20A in LUAD remains largely unknown." (PMID 30105795, 2018). "After silencing KIF20A, lung cancer cell cycle arrested in G1 phase and apoptosis increased." (PMID 30105795, 2018). "The results of bioinformatics analysis showed that KIF20A was an oncogene in lung cancer." (PMID 30105795, 2018). "We confirmed that three kinesin genes (KIF4A, KIF20A, and KIF11) have some influence on the occurrence and progression of lung cancer." (PMID 41462522, 2025). "Overall, SH3PXD2A-AS1 can promote the expression of target genes such as FOXM1, CENPF and KIF20A by binding to the DHX9 protein, thereby promoting the cell cycle progression and cell proliferation of NSCLC, and promoting the growth of lung cancer." (PMID 35410446, 2022). "Compared with normal tissues, the expression of ADM2, CLIC6, KIF20A, LAD1, MUC5B, and TNS4 was up-regulated, and the expression of ATG16L2, KCNK3, MAFF, NKD1, and SPATA13 was down-regulated in lung cancer tissues." (PMID 34804921, 2021). "After knocking down of KIF20A, the percentage of LUAD cells in G1 phase significantly increased, while the percentage of cells in S phase markedly decreased, indicating that downregulation of KIF20A could arrest lung cancer cells in G1 phase." (PMID 30105795, 2018).
melanoma (14 papers, 2013 to 2025). A malignant, usually aggressive tumor composed of atypical, neoplastic melanocytes. "It is well known that while tumor recurrence has a very significant relationship with patient prognosis, this indirectly suggests that KIF20A is associated with survival in melanoma patients, which is consistent with the results of our study." (PMID 33912448, 2021). "Additionally, TPX2 is strongly co-expressed with KIF20A, a factor implicated in the development and progression of many cancer types, including melanoma and cervical squamous cell carcinoma." (PMID 40362354, 2025). "Furthermore, KIF20A is suggested to be a novel melanoma-associated antigen, and a potential diagnostic and prognostic marker of melanoma." (PMID 27941992, 2016). "As KIF20A and GPR87 are glycolysis-related genes with poor prognostic potential for patients with melanoma, we next examined the effects of KIF20A and GPR87 on glycolytic ability within melanoma cells." (PMID 34659201, 2021). "When analyzing the potential biological functions of these proteins in melanoma, we found that silencing SEMA4D or IFITM1 promoted, while silencing KIF20A or GPR87 inhibited the proliferation of melanoma cells in vitro." (PMID 34659201, 2021). "Survival curves showed that high expression of FOXM1,\ EXO1, KIF20A, TPX2, and CDC20 in melanoma patients with 5 of the top 10 hub genes was associated with reduced overall survival (OS)." (PMID 33912448, 2021). "FOXM1, KIF20A, TPX2, CDC20, and EXO1 are hub genes of melanoma prognostic, and their high expression is strongly associated with low prognosis in melanoma patients." (PMID 33912448, 2021). "FOXM1, EXO1, KIF20A, TPX2, and CDC20 are prognosis-associated core genes of melanoma, and their high expression correlates with the low prognosis of melanoma patients and can be used as biomarkers for melanoma diagnosis, treatment, and prognosis prediction." (PMID 33912448, 2021). "After transfection with KIF20A-siRNA or GPR87-siRNA, levels of lactate, ATP and glucose uptake as well as extracellular acidification rates were all significantly reduced in these melanoma cells." (PMID 34659201, 2021). "The protein expression of FOXM1, KIF20A, TPX2, CDC20, and EXO1 was higher in melanoma than in paraneoplastic tissues, consistent with our analysis results." (PMID 33912448, 2021). "Results from the immunohistochemistry assay revealed that SEMA4D and IFITM1 were down-regulated, while KIF20A and GPR87 were over-expressed in melanoma tissue." (PMID 34659201, 2021). "Additionally, the AUC for KIF20A in predicting response to PD-1 inhibitors was higher than for CD274 and PDCD1, a finding confirmed in another cohort of 28 melanoma patients undergoing anti-PD-1 checkpoint inhibition therapy." (PMID 39555078, 2024). "In this study, we present the first evidence that SEMA4D, IFITM1, KIF20A and GPR87 may possess a prognostic value for melanoma." (PMID 34659201, 2021). "FOXM1, KIF20A, TPX2, CDC20, and EXO1 could be used as biomarkers for melanoma diagnosis, treatment, and prognosis prediction." (PMID 33912448, 2021). "Based on these results, it seems likely KIF20A and GPR87 may function as oncogenes through their capacity to regulate glycolysis within melanoma cells." (PMID 34659201, 2021). "Moreover, our findings provide the first indication that KIF20A and GPR87 can regulate the glycolytic ability of melanoma cells." (PMID 34659201, 2021). "In specific, the results of our in vitro experiments suggest that SEMA4D and IFITM1 may function as tumor suppressor genes while KIF20A and GPR87 may function as oncogenes in melanoma." (PMID 34659201, 2021). "In conclusion, by combining the WGCNA analysis method with differentially expressed gene analysis, our study identified the genes FOXM1, KIF20A, TPX2, CDC20, and EXO1 highly correlated with survival melanoma patients and have the potential to serve as a prognostic biomarker in melanoma." (PMID 33912448, 2021).
melanoma (continued). "Finally, SEMA4D and IFITM1 may function as tumor suppressor genes, while KIF20A and GPR87 may function as oncogenes in melanoma as revealed from results of in vitro experiments." (PMID 34659201, 2021). "Also, it has been shown that skin tumor thickness in KIF20A-positive patients with primary melanoma is significantly greater than skin tumor thickness in patients negative for this gene and that KIF20A-positive patients are more likely to relapse earlier." (PMID 33912448, 2021).